MTOR (mechanistic target of rapamycin kinase)
Diseases named in the same sentence as MTOR in open-access papers (continued):
Sharing a sentence is not in itself a finding about the gene and the disease.
lung cancer (continued). "While combined mTOR, IGF1R, and MEK inhibition shows significant tumor regression in K-RasG12C–driven lung cancer mouse models, replacing the MEK inhibitor with a K-RasG12C inhibitor in combination demonstrates greater efficacy, specificity, and tolerability." (PMID 34222333, 2021). "In particular, several crucial molecular pathways involved in the efficacy of curcumin as an anti-lung cancer drug involve the vascular endothelial growth factor (VEGF), EGFR, nuclear factor-κB (NF-κB), and mammalian target of rapamycin (mTOR) pathways." (PMID 34207313, 2021). "More promisingly, two independent studies have shown that the efficacy of the KRASG12C inhibitor ARS-1620 was increased when combined with mTOR and an IGF1R inhibitor and PI3K inhibitor in lung cancer cells and in vivo models." (PMID 34946644, 2021). "Knock down of KLF5 suppresses the resistance to anti-cancer cisplatin in lung cancer cells, through inactivation of the PI3K/Akt/mTOR pathway." (PMID 33573362, 2021). "Consistently, the cell cycle-and apoptosis-related protein expressions of mTOR, STAT3, Bcl-2, and cyclin D1 significantly increased in A549 lung cancer cells after treatment with 100 ng/ml leptin." (PMID 33708630, 2021). "FBLN3 suppresses tumor invasiveness through inhibition of the MAPK pathway in lung cancer, and it enhances tumor cell growth and induces epithelial–mesenchymal transition (EMT) by activation of the AKT/mTOR pathway in cervical cancer." (PMID 34769264, 2021). "In many cancers, including lung carcinoma, the PI3K/AKT/mTOR pathway is hyperactive, thus blocking apoptosis through the regulation of downstream signaling molecules, such as inhibiting the activation of Caspase-7, as well inactivating Bcl-2 family members." (PMID 33393627, 2021). "In lung cancer, piR-55490 inhibits cell growth by binding to the 3′UTR region of mTOR to induce the degradation of mTOR." (PMID 32351883, 2020). "In our study, we found that PD-L1 promotes lung cancer cells proliferation, migration and invasion by activating PI3K/Akt/mTOR and Erk pathway." (PMID 32632098, 2020). "In lung cancer, several studies have shown that miR-99a-5p acts as a tumor-suppressive miRNA by targeting critical oncogenic pathways, including AKT1 and mTOR signaling." (PMID 32932948, 2020). "Based on our experimental data, we concluded that circHIPK3 promoted lung cancer progression, at least in part, via sponging miR-381-3p and modulating the AKT/mTOR signaling pathway." (PMID 33817257, 2020). "In conclusion, the silencing of circHIPK3 inhibited lung cancer progression, at least in part, by sponging miR-381-3p and inactivating the AKT/mTOR signaling pathway." (PMID 33817257, 2020). "Among identified pathways, we highlight the EGFR, FGFR1, KRAS, and PI3K-AKT signaling, and other well-known lung cancer pathways, such as MAPK and mTOR." (PMID 32726984, 2020). "Altogether, circHIPK3 knockdown inhibited lung cancer progression, at least in part, by targeting miR-381-3p to regulate the AKT/mTOR pathway in vivo." (PMID 33817257, 2020).
lung cancer (continued). "Results from another in vivo lung cancer study conducted on LLC cells indicated that both lung cancer metastasis and tumoral growth were suppressed through the inhibition of mTOR, as rapamycin prevented movement to distant nodes." (PMID 36046386, 2020). "Simultaneous application of the dual PI3K/mTOR inhibitor BEZ235 and the HDAC inhibitor trichostatin A (TSA) synergistically suppressed growth and metastasis of lung cancer cells in vitro and in vivo by inactivating both Akt and mTOR and down-regulating HDAC." (PMID 31010254, 2019). "In lung cancer, several inhibitors of PI3K/mTOR/Akt axis have been evaluated in clinical trials as single agent and/or combination therapies demonstrating relevant adverse events without a solid clinical benefit." (PMID 31404976, 2019). "PRR14 is amplified and aberrantly overexpressed in lung cancer, and promotes lung cancer cells proliferation through the activation of the PI3K/AKT/mTOR signaling pathway." (PMID 31596887, 2019). "We report here that TM4SF1 regulates lung cancer chemo-sensitivity and apoptosis through the DDR1-activated AKT/mTOR signaling pathway." (PMID 31142317, 2019). "Further studies showed that NAP exhibits anti-proliferative activity against human lung cancer H1299 cells, by inhibiting the PI3K/AKT/mTOR pathway." (PMID 31226829, 2019). "Mechanically, FBXO22 promotes NSCLC cell growth through inhibiting LKB1/AMPK/mTOR signaling pathway, which reinforces the oncogene function of FBXO22 in lung cancer." (PMID 31217475, 2019). "Identification of the FBXO22/LKB1/AMPK/ mTOR axis in this study not only provides great insight into how LKB1 kinase activity is regulated, but also highlights FBXO22 as a potential target for lung cancer therapy." (PMID 31217475, 2019). "Mechanistically, WA inhibited oncogenic signaling in lung cancer, namely, the mTOR/STAT3 pathway, indicating that WA exerted an anti–lung cancer effect." (PMID 31319622, 2019). "Mechanistic characterization revealed that this drug combination abrogated expression and activation of membrane receptors and downstream signaling proteins crucial in lung cancer: EGFR, MET, PAK1, PKCι, ERK1/2, AKT, YAP1 and mTOR." (PMID 31660987, 2019). "In specific cell types, such as human lung cancer H460 cells, glioblastoma U87 cells, and nasopharyngeal carcinoma cells, low-dose RAPA can slightly reduce the amount of total mTOR." (PMID 30874538, 2019). "Previous studies indicate that the SLIT/ROBO pathway acts as master regulator for multiple oncogenic signalling pathways including the CD20, mTOR, VEGF and EGFR pathways in several cancer types including lung cancer, colon cancer and lymphoma." (PMID 30857150, 2019). "In lung cancer cells, consistent with our results, SEMA3F downregulates the hypoxia-inducible factor-1α (HIF-1α) protein and VEGF mRNA levels by blocking the Akt-mTOR signaling pathway." (PMID 30532711, 2018). "Based on these preclinical data demonstrating synergy of palbociclib in combination with everolimus, and the demonstrated tolerability of palbociclib in patients with advanced lung cancer, a clinical trial with combined CDK4/6 and mTOR inhibition is warranted." (PMID 30647837, 2018). "SEMA3F also inhibits Akt-mTOR signaling in several other cell lines expressing NRP2, including lung cancer cells, melanocytes, Jurkat T lymphocytes, and ECs." (PMID 30532711, 2018). "Oral administration of G. lucidum extracts suppressed lung cancer tumor growth in mice and suppressed the activation of PKB (Akt), mechanistic target of rapamycin (mTOR), S6 kinase, and 4E-BP1 in lung cancer cells." (PMID 29872510, 2018). "Different signaling pathways such as AKT/mTOR pathway, STAT1, and STAT3 pathway, ERK pathway played a critical role in the progression of lung cancer." (PMID 29788985, 2018). "In lung cancer, AKAP1 expression correlates with high levels of Myc, mTOR phosphorylation and reduced patient survival." (PMID 28569781, 2017).
lung cancer (continued). "miR-145 inhibits lung cancer cell migration and invasion by targeting PDK1 via the mTOR signaling pathway." (PMID 29340099, 2017). "In H661 and H1299 lung cancer cells, Western blot analysis demonstrated that diminished CD164 expression resulted in decreased Akt and mTOR phosphorylation, and decreased CXCR4 activation." (PMID 28903328, 2017). "The mechanism of FDG uptake within lung cancer cells involves glucose metabolism, hypoxia, angiogenesis, and the mammalian target of rapamycin (mTOR) signaling pathway; mTORC1 activity affected the amount of FDG uptake within lung cancer cells." (PMID 28980429, 2017). "Along with other groups, we have have found that antroquinonol inhibits lung cancer and liver cancer cells by modulating the AMP-activated protein kinase (AMPK) or phosphatidylinositol-3-kinase (PI3K)/ mammalian target of rapamycin (mTOR) pathways." (PMID 29130448, 2017). "In lung cancer cells, BMP-2 regulates cellular transformation by activating the PI3K/mTOR pathway, which was completely inhibited by the mTOR inhibitor rapamycin." (PMID 28733469, 2017). "There is already evidence that mTOR and its upstream activator, IGF1R, are the direct targets of miR-99a in lung cancer, esophageal squamous cell carcinoma, acute lymphoblastic leukaemia as well as HCC." (PMID 28624790, 2017). "In the current study, we demonstrated that miR-206 overexpression inhibited HGF-induced lung cancer EMT, metastasis and angiogenesis by targeting c-Met and its downstream PI3k/Akt/mTOR (mammalian target of rapamycin) pathway." (PMID 26919096, 2016). "Among the differentially expressed miRNAs, miR-208a promoted lung cancer cell proliferation and decreased cell apoptosis by targeting p21 and AKT/mTOR pathway." (PMID 26754670, 2016). "In this study, we reported that curcumin not only inhibits HGF-induced EMT of lung cancer cells, but also suppresses angiogenesis of HUVECs, and the mechanism is related to regulation of c-Met-dependent PI3K/Akt/mTOR signaling pathways." (PMID 27525306, 2016). "We next used Western blotting to determine how the phosphorylation of ACC, TSC2, and mTOR correlate with the phosphorylation of AMPK after transfection with vectors (wild-type PKR, mutant PKR, and Luc) in H1299, A549, and H322 lung cancer cells." (PMID 25798539, 2015). "Interplay between the PI3K/mTOR and MAPK pathways has been identified as a critical factor in oncogenesis, specifically to that of lung cancer." (PMID 26098947, 2015). "Mutant NRAS was also shown to activate the PI3K/mechanistic target of rapamycin (mTOR)-signaling cascade and combined inhibition of MEK and PI3K was synergistic in certain NRAS mutant cell lines of melanoma, lung cancer and neuroblastoma." (PMID 26544513, 2015). "In our study, CX-4945 induced autophagosomes more potently than rapamycin, a well-known mTOR inhibitor in EGFR-mutant, lung cancer cells with T790M." (PMID 25486409, 2014). "As radiation therapy (RT) is a commonly used treatment in many types of cancers, including lung cancer, we next chose to analyze how PI3K/Akt/mTOR inhibition can affect radiosensitivity." (PMID 25221647, 2014). "In addition, AMPK-independent actions of metformin have also been reported which include inhibition of mTOR signaling either through RAG GTPases, through enhancement of PRAS40-RAPTOR association in glioma, or through activation of JNK/p38 MAPK-mediated apoptotic pathway to inhibit lung cancer." (PMID 25365944, 2014). "Colon cancer cells were treated with inhibitors of ERK, Akt, and mTOR signaling pathways and the resulting effects on PDF and MAP1D mRNA levels were determined by qPCR for colon and lung cancer cell lines." (PMID 23815882, 2013).
lung cancer (continued). "Both temsirolimus and everolimus inhibited the phosphorylation of p70S6K and 4E-BP1, which are downstream targets of the mTOR pathway, and reduced the viability of EGFR mutant lung cancer cells, PC-9, and HCC827, even in the presence of HGF in vitro." (PMID 23690929, 2013). "Chrysin, a naturally occurring flavone chemically extracted from the passion flowers Passiflora caerulea and Passiflora incarnata, leads to growth inhibition and apoptosis of lung cancer cells via AMPK activation and inhibition of AKT/mTOR." (PMID 23875169, 2013). "The present study suggests that fucoidan exhibits anti-metastatic effect on A549 lung cancer cells via the down-regulation of ERK1/2 and Akt-mTOR as well as NF-kB signaling pathways." (PMID 23226337, 2012). "Other ATP competitive mTOR inhibitors such as KU-0063794, WYE-354, WYE-132, OXA-01 are currently under clinical research in patients with solid tumors including lung cancer patients." (PMID 24281308, 2012). "Inhibition of PI3K/AKT/mTOR signaling through pharmacologic and genetic approaches induces antiproliferative effects on certain NSCLC cell lines and in lung cancer mouse models." (PMID 22355357, 2012). "In this section, we describe PI3K pathway inhibitors that have reached clinical trials for the treatment of lung cancer, considering four different categories: PI3K inhibitors, dual PI3K- mTOR inhibitors, Akt inhibitors and mTOR inhibitors." (PMID 24281308, 2012). "Small molecules or kinase inhibitors targeting growth factor receptors and the PI3K/AKT/mTOR, Src/Stat, p38, and ATM/CHK2 pathways were extensively investigated for cancer treatment, both preclinically and clinically, including treatment for lung cancers." (PMID 22348039, 2012). "The combined effects of inhibiting MEK with PD-0329501 and mTOR with rapamycin or its analog AP-23573 (ARIAD Pharmaceuticals/Merck) were examined in human NSCLC cell lines, as well as in animal models of human lung cancer." (PMID 23085539, 2012). "Given the synergism seen between PI3K inhibitors and rapamycin in lung cancer cell lines, a dual PI3K/mTOR inhibitor that has been given to solid tumor patients in phase I clinical trials, NVP-BEZ235, was studied." (PMID 22355357, 2012). "mTOR inhibition has also been known to reverse in vitro acquired resistance to endocrine therapy and EGFR inhibitors of breast and lung cancers, respectively." (PMID 21364753, 2011). "EPA and DHA-induced autophagy enhanced lung cancer cell apoptosis, and further investigations indicated that ω-3 LCPUFAs induced autophagy via modulating the phosphatidylinositol 3-kinase (PI3K)/AKT/mTOR pathway." (PMID 39834867, 2025). "Furthermore, curcumin inhibited the Wnt and mTOR signaling pathways through the downregulation of UCA1, suggesting that curcumin exerts its anticancer effects in lung cancer by targeting the UCA1–Wnt/mTOR axis (Wang W.-H." (PMID 41322307, 2025). "Similarly, in non‐small cell lung cancer, sertraline combined with erlotinib enhanced autophagy through the AMPK/mTOR axis." (PMID 40874450, 2025). "This study suggests that the ERK and PI3K/mTOR pathways each mitigate the effects of inhibition of the other and that combinatorial inhibition is a potential strategy for treating KRASG12C-dependent lung cancer." (PMID 39025835, 2024). "The results showed that 0.5% ACN diet inhibited the development of urethane-induced lung cancer in C57BL/6J mice, and the mechanism might be through modulating of AMPK/mTOR signaling pathway to regulate tumor fatty acid and energy metabolism." (PMID 38716355, 2024). "But the combined evaluation of mTOR and STAT3 genes suggested that these also could be used as a critical gene set for predicting lung cancer patient outcomes." (PMID 38886756, 2024). "MTOR inhibition, however, reversed the resistance to EGFR-TKIs in lung cancer." (PMID 38397056, 2024).
lung cancer (continued). "An in vitro study on lung cancer revealed that adiponectin can suppress the proliferation of lung cancer cells by inhibiting the PI3K/Akt signaling pathway and the phosphorylation of mTOR (mammalian target of rapamycin)." (PMID 38571500, 2024). "An inhibitor of HSP90AA1 was reported to remarkably induce apoptosis and suppress cell proliferation in lung cancer through an ERK/AKT-dependent mechanism and to induce autophagic cell death in osteosarcoma by suppressing AKT/mTOR signaling, highlighting its importance in cancer biology." (PMID 39518920, 2024). "Gefitinib was shown to promote autophagy in lung cancer cell lines, as indicated by LC3II lysosomal localization, increased ATG5 and ATG7 expression at the mRNA or protein levels, and reduced phosphorylation of the PI3K/Akt/mTOR pathway." (PMID 39272847, 2024). "In A549 lung cancer cells treated with 100 μM C3G, AMPK/mTOR, an important energy metabolism-related pathway, was significantly altered, AMPK was activated, and its downstream target gene mTOR was significantly downregulated." (PMID 38716355, 2024). "In total, 57.1% of these patients had no therapy option, since PIK3CA (14.3%), IDH2 (7.1%), and MTOR (7.1%) are not actionable lung cancer genes." (PMID 39769478, 2024). "In lung cancer, an attenuated lentogenic isolate of Newcastle disease virus (NDV), strain FMW (NDV-FMW) induced caspase-dependent apoptosis in lung cancer spheroids and triggered autophagic degradation by inhibition of the AKT/mTOR pathway." (PMID 37283735, 2023). "Also, natural products (NP) activate apoptotic pathways in lung cancer cell including p‐JNK, Akt/mTOR, PI3/ AKT\ and Bax, Bcl2, but suppressed AXL phosphorylation." (PMID 37697969, 2023). "In this review, the terms "Akt/mTOR", "Alkaloid", "flavonoid", and "lung cancer" were searched without any limitation in search criteria in Scopus, PubMed, Web of Science, and Google scholar engines." (PMID 36721812, 2023). "Moreover, SHP2 mediates the activation of several receptor tyrosine kinases and downstream effectors of multiple signaling pathways (e.g., ALK-MAPK, PI3K/AKT/mTOR), and has been identified as a common resistance node in subsets of ALK-rearranged lung cancers." (PMID 38032104, 2023). "Notably, USP5 is highly expressed in lung cancer, USP5 overexpression promoted the proliferation and migration in the lung cancer cell lines, H1299 and A549, while knockdown of USP5 inhibited these via regulating the PARP1-mediated mTOR signaling pathway." (PMID 37060095, 2023). "Additionally, the PI3K/Akt/mTOR, VEGFR1/2, and Wnt pathways, which are promising therapeutic targets for lung cancer, were activated, showing high drug sensitivity under 3D-HTS using the 3D-subcultured cells." (PMID 37766900, 2023). "In a study with the lung cancer cell lines LLC and A549, lung carcinoma cell-derived exosomes suppress DC costimulatory molecule expression, inflammatory response and promote DCs autophagy via MALAT1, a transcript that stimulates the AKT/mTOR pathway." (PMID 37915578, 2023). "The present study identified six hub genes that were related to lung cancer, including mTOR, NF1, CHD7, ETS1, IL-6, and COL1A1, which might be a potential target for lung cancer." (PMID 36211008, 2022). "PPII has been demonstrated to sensitize gefitinib to lung cancer cells by inhibiting PI3K/AKT/mTOR signaling, a canonical negative autophagy regulating signal." (PMID 36233191, 2022). "In lung cancer, the alteration of upstream regulators, such as activating the epidermal growth factor receptor (EGFR) can lead to sustained activation of the PI3K/Akt/mTOR cascade." (PMID 36180880, 2022). "It was reported that both compounds 15 and 16 showed high inhibitory activity against A549 lung cancer cells, and both could induce apoptosis and induce autophagy to exert anti-tumor effects through the PI3K/mTOR signaling pathway." (PMID 36210835, 2022).